APOE (apolipoprotein E)
Diseases named in the same sentence as APOE in open-access papers (continued):
Sharing a sentence is not in itself a finding about the gene and the disease.
cardiovascular disease (continued). "This is consistent with previous studies that have reported a decreased risk of cardiovascular disease (CVD) among carriers of the APOE ε2 allele." (PMID 38540308, 2024). "APOE-ε4 was initially recognized clinically in association with elevated cholesterol and cardiovascular disease." (PMID 37556539, 2023). "Atherosclerosis-prone apolipoprotein E-deficient (Apoe-/-) mice are used as an animal model of atherosclerosis and more generally for understanding the pathophysiology of cardiovascular diseases." (PMID 37974269, 2023). "The evidence further highlights that APOE-ε4 carriers are at elevated risk of cause-specific mortality including cardiovascular diseases, and ischemic heart disease, among other mortality causes." (PMID 37434484, 2023). "Cardiovascular disease (CVD) is associated with the apolipoprotein E (APOE) gene and lipid metabolism." (PMID 37796905, 2023). "In order to mimic the metabolic dysregulation commonly associated with cardiovascular disease, we crossed these mice onto the hyperlipidaemic ApoE knock-out background." (PMID 35653516, 2023). "What we know is that brain amyloid deposition and gait performance are both related to cognition and share several risk factors, such as diet and smoking, cardiovascular disease and expression of the APOE ε4 allele." (PMID 37762384, 2023). "It is estimated that APOE E3/E4 and E4/E4 variants are associated with higher risks (22 and 45%, respectively for developing cardiovascular disease than E3/E3)." (PMID 35387194, 2022). "Although the relationship between ApoE genotype, cardiovascular diseases, and neurodegenerative disorders is well established, the diagnostic role of quantitative plasma ApoE concentration measurements are more controversial." (PMID 36380282, 2022). "The association between APOE genotypes and cardiovascular disease (CVD) is partially mediated by LDL-cholesterol concentration but persists after adjusting for lipid levels and other cardiovascular risk factors." (PMID 36361733, 2022). "The association of the APOE genotype with cardiovascular disease is partially mediated by its influence on low-density lipoprotein (LDL) cholesterol concentrations." (PMID 36361733, 2022). "We also considered the influence of other variables known to impact cognitive function such as education level, alcohol consumption, the presence of apolipoprotein E4 gene (APOE-ε4) and risk of cardiovascular disease." (PMID 35895279, 2022). "Because in humans APOE alleles have a major impact on aging-associated diseases, particularly cardiovascular disease, type 2 diabetes and late-onset AD we focused on the effect of the Apoe variants we identified in the degu." (PMID 35860672, 2022). "This review article focuses on lipoprotein transport-dependent and -independent mechanisms by which apoE deficiency or polymorphisms contribute to cardiovascular disease, metabolic disease, and neurological disorders." (PMID 36077289, 2022). "It has been found that aging‐related processes can substantially impact the role of lipid‐related genes (including ApoB and ApoE allele) in regulation of TC and onset of cardiovascular disease." (PMID 34913545, 2022). "In conclusion, receiving information on increased personal genetic risk (carrier status of APOE ε4) for cardiovascular diseases provided the motivation for improvements in health behavior." (PMID 36028843, 2022). "This review article focuses on lipoprotein transport-dependent and -independent mechanisms, by which apoE deficiency or polymorphism contribute to cardiovascular disease, metabolic disease, and neurological disorders." (PMID 36077289, 2022).
cardiovascular disease (continued). "Although the ApoE e4 allele is generally considered as a strong susceptible gene for cardiovascular diseases and AD, the significant relationship between ApoE e4 and VCID is currently not illustrated." (PMID 36012981, 2022). "Lead SNPs nearby GCKR, FTO, ZPR1, and APOE were associated with various traits including cardiovascular diseases and/or PhenoAge biomarkers." (PMID 34038024, 2021). "Serum levels were positively associated with microvascular inflammation but knockouts developed stronger cardiovascular diseases with apolipoprotein E deficiency, and progranulin expression was low in cardiovascular lesions." (PMID 34836380, 2021). "Only one out of the four selected SNPs (ApoE rs7412 SNP) was found to be associated with the risk of cardiovascular disease." (PMID 33437219, 2021). "Education, apolipoprotein E-ε4 allele, and comorbid cardiovascular disease influenced the observed associations." (PMID 34228116, 2021). "Regarding the relationship between those polymorphisms and the susceptibility to cardiovascular diseases, only one of the four investigated SNPs, (rs7412) ApoE gene, displayed significant association." (PMID 33437219, 2021). "Recognized risk factors for AD are family history, advanced age, the apolipoprotein E (APOE) ε4 allele genotype, illiteracy, cardiovascular disease risk factors, lifestyle, and psychosocial factors." (PMID 32933034, 2020). "It is known that disturbance of the homeostatic state, which is correlated to apolipoprotein E function, is associated with cardiovascular diseases and is often attributed to nutrition habits and lifestyle." (PMID 32366041, 2020). "Apolipoprotein E (apoE) is an important regulator of lipid metabolism in the brain, and its polymorphism has been associated with cardiovascular diseases and neurodegenerative diseases." (PMID 31991844, 2020). "APOE genetic variants also affect human longevity due to the transport of lipids and risks associated with cardiovascular diseases." (PMID 31450785, 2019). "When further adjusted for eGFR, UAE, a cardiovascular disease history and use of antihypertensive medication and glucose and lipid lowering drugs, plasma ApoE remained associated with an elevated FLI (Model 3, β = 0.201, P<0.001)." (PMID 31386691, 2019). "The first example is the APOE gene, a gene which expression has been associated with Alzheimer and cardiovascular diseases and with genetic variants at the TOMM40/APOE/APOC1 locus near the gene also associated with longevity." (PMID 29228364, 2018). "In the past 25 years, genetically altered mouse models, such as the apolipoprotein E (ApoE) deficient (Apoe−/−) mouse, have been studied to understand the underlying pathophysiological mechanisms of cardiovascular disease and the development of therapies." (PMID 29615808, 2018). "Different isoforms of ApoE have been associated with susceptibility to various diseases including Alzheimer’s and cardiovascular diseases." (PMID 30496280, 2018). "Conversely, inhibition of NF-κB in vascular cells often exhibits therapeutic effects on cardiovascular diseases, such as the amelioration of vascular atherosclerotic lesion in apolipoprotein E (ApoE)-deficient mice." (PMID 29968158, 2018). "ApoE despite apoA1 is associated with cardiovascular disease due to formation of cholesterol plaques within the arteries." (PMID 28695482, 2017). "The association of ApoE e4 with the development of dyslipidemia and cardiovascular disease has been described for the past two decades and is now well established." (PMID 28480219, 2017). "Using longitudinal data, Reecha Sofat and colleagues probe the association between blood levels of ApoE and risk of cardiovascular disease." (PMID 27755538, 2016). "Absolute risk regression was used to estimate risk differences in the outcome adjusting for demographic variables, clinical and behavioral risk factors, subclinical cardiovascular disease, and ApoE genotype." (PMID 27875557, 2016).
cardiovascular disease (continued). "The association of APOE genotype with circulating apolipoprotein E (ApoE) concentration and cardiovascular disease (CVD) risk is well established." (PMID 27755538, 2016). "Variants of APOE affect blood lipid levels, the risk of cardiovascular disease, and survival in affluent populations." (PMID 27356285, 2016). "APOE4 is associated with an increased risk for cardiovascular disease (CVD), generally attributed to the higher plasma triglyceride and LDL cholesterol concentrations observed in APOE ε4 carriers." (PMID 27457486, 2016). "In humans, the APOE variants are known for their roles in atherosclerosis, cardiovascular disease, Alzheimer disease, aging, and longevity." (PMID 27177774, 2016). "Although ApoE−/− mice have been used mostly for cardiovascular disease research, the underlying pathology of neurological disorders in ApoE−/− mice are still inconclusive and contradictory." (PMID 27809235, 2016). "These genetic polymorphisms of APOE gene are associated with cardiovascular diseases and neurodegenerative diseases." (PMID 27078154, 2016). "Taken together, our results indicate that MR in ApoE-KO mice was associated with a modest stimulatory response despite predisposition to cardiovascular disease." (PMID 25744495, 2015). "Epidemiological studies have indicated that there is a notable association between APOE gene polymorphism and a serious risk of cardiovascular disease or certain infectious diseases." (PMID 25574218, 2015). "The APOE e4 allele is associated with an increased risk for cardiovascular diseases, including stroke, and coronary heart disease." (PMID 25325355, 2014). "Apolipoprotein E (apoE) is a member of apolipoprotein family, and its gene polymorphisms seem to have some impact among patients with cardiovascular disease." (PMID 24456740, 2014). "Second, the APOE e4 allele is associated with an increased risk for several aging related diseases, including AD and cardiovascular diseases, whereas the APOE e2 allele has been associated with a decreased risk for these diseases." (PMID 25325355, 2014). "The APOE gene polymorphisms were associated with diseases of the respiratory system and cardiovascular disease." (PMID 24571688, 2014). "This study has demonstrated that daily injections of OCN produced significant effects on glucose and lipid metabolism, as well as improving insulin sensitivity, in ApoE-KO mice, all of which represent risk factors of cardiovascular disease." (PMID 24708830, 2014). "Because of its key role in the regulation of lipid metabolism ApoE was first recognized for its role in cardiovascular diseases (CVD)." (PMID 25071563, 2014). "Apolipoprotein E (APOE) genotypes are associated with cardiovascular disease (CVD) and lipid levels." (PMID 23613766, 2013). "Absence or structural mutations of APOE cause significant disorders in lipid metabolism and cardiovascular diseases." (PMID 22074026, 2011). "Like low IGF-1 levels, ApoE ε4 was previously associated with an increased risk of developing cardiovascular disease and neurodegenerative disease." (PMID 21418511, 2011). "An illustrative example of this in the general population, inherited variation in APOE alleles, is provided by the large role that oxidative stress probably plays in cardiovascular disease genesis." (PMID 21223544, 2011). "Polymorphisms at the apoE gene (APOE) have been associated with cardiovascular disease, lipid levels and lipid-lowering response to statins." (PMID 22074026, 2011). "Third, as the study design was cross-sectional, we cannot directly evaluate the long-term impact of the APOE polymorphism on the physiological complexity and incidence of cardiovascular diseases." (PMID 19890394, 2009). "The outcomes showed that compared with the advice that followed conventional dietary guidelines, the subjects who carried the APOE ε4 allele and received the gene‐based nutritional recommendations had a significantly lower risk of developing cardiovascular diseases." (PMID 41567168, 2026).
cardiovascular disease (continued). "In addition, APOE has broader physiological significance beyond the nervous system, and it has been strongly implicated in cardiovascular diseases." (PMID 40943807, 2025). "Besides its role in AD and neurodegeneration, the APOE ε4 allele is also a well-established genetic risk factor for cardiovascular disease (CVD), primarily due to its effects on lipid metabolism and inflammation." (PMID 40671162, 2025). "Different APOE isoforms (E2, E3, E4) are associated with different risk of cardiovascular disease." (PMID 41234028, 2025). "Consequently, there appears to be a weaker association between the expression of the APOE gene ε2 allele and cardiovascular diseases." (PMID 38540308, 2024). "The ApoE e4 allele is one of the most notorious common genetic risk factors, with the potential to increase AD risk up to 15‐fold when homozygous, and further adverse effects on lipid profiles and cardiovascular diseases." (PMID 38376028, 2024). "Since the APOE gene is also associated with increased of cardiovascular disease, this genetic risk factor may contribute to the observed mediating role of CVRFs." (PMID 39081968, 2023). "A possible explanation for the higher AD risk in APOE ε4 carrier men at an older age is that the age-adjusted period of prevalence for cardiovascular disease (CVD) related to APOE genotype is higher in men than in women (18.6% in the ε4 group for men and 9.9% for ε4 women)." (PMID 37680541, 2023). "APOE isoforms can also heavily interfere with other risk factors for cardiovascular diseases (CVD)." (PMID 37185708, 2023). "ApoE variation has been linked to cardiovascular disease (CVD) risk." (PMID 37134097, 2023). "Cognitively normal older women carrying at least one APOE ɛ4 allele, may be particularly vulnerable to the effects of cardiovascular disease risk on cortical tau deposition." (PMID 35233525, 2022). "Second, APOE ε4 could increase the risk of cardiovascular disease, which is in turn associated with the pathology of AD." (PMID 35624902, 2022). "We therefore genotyped hESCs for these common variants and identified 22 cell lines with a “universal donor” O blood type, a cell line (Elf1) likely resistant to HIV infection, and three cell lines carrying the APOE “e4/e4” risk haplotype for cardiovascular disease and AD." (PMID 35176222, 2022). "Although ApoE KO mice are widely used to model atherogenesis, the early lesion more resembles fatty streak of the nascent atherosclerotic plaque than the complex lesion associated with human cardiovascular disease." (PMID 35624851, 2022). "APOE polymorphisms are associated with all types of tumors and cardiovascular diseases (CVD)." (PMID 36057714, 2022). "Our findings suggest that cognitively normal older women carrying at least one APOE ɛ4 allele, may be particularly vulnerable to the effects of cardiovascular disease risk on early tau deposition." (PMID 35233525, 2022). "Therefore, we examined the role of sex and APOE ɛ4 status in modifying the effect of cardiovascular disease risk on cortical tau in CN older adults." (PMID 35233525, 2022). "This is a well-established mouse model of cardiovascular disease, in which a diet rich in fat and cholesterol on an ApoE deficient background accelerates the development of hypercholesteremia, atherosclerotic plaque development and inflammation of the skin and other tissues." (PMID 36685213, 2022). "One of the potential mechanisms for the association of the APOE locus with cardiovascular disease could be through inflammation-related mechanisms." (PMID 36361733, 2022). "ApoE ε4 allele is a risk factor for the onset of Alzheimer’s and cardiovascular diseases." (PMID 34631220, 2021). "Higher levels of ApoE are a risk factor for cardiovascular diseases." (PMID 34444289, 2021). "ApoE abnormality represents a well-known risk factor for cardiovascular diseases." (PMID 34575848, 2021).
cardiovascular disease (continued). "ApoE isoform has recently been suggested to increase the risk for severity of COVID-19 infection and this can occur independently of pre-existing morbidities including dementia, cardiovascular disease, and diabetes." (PMID 33800954, 2021). "As oxidative stress is an unifying mechanism for many cardiovascular diseases risk factors, we might lack one of the contributing factors for developing accelerated atherosclerotic plaques in ApoE−/− mice exposed to CS under NOEC conditions." (PMID 33825214, 2021). "APOE‐ε4 carriers have an increased risk of cardiovascular disease that may contribute to earlier death." (PMID 32472747, 2020). "ApoE-/- mice represent a well-established model for the study of atherosclerosis, a disease characterized by the build-up of lipid- and inflammatory cell-rich plaques within arteries, which underlies the majority of cardiovascular diseases." (PMID 32422323, 2020). "Using mouse deficiency in IKKε and apolipoprotein E (Apoe), we recently showed that IKKε is a key player in the pathogenesis of the cardiovascular disease; deficiency of IKKε has been suggested to have an anti-inflammatory effect and to inhibit malignant transformation." (PMID 32064021, 2020). "APOE polymorphism seemed to have some effect on patients with cardiovascular disease." (PMID 31521122, 2019). "However, one of the most notable associations to be examined is between APOE alleles and cardiovascular disease (CVD)." (PMID 30884759, 2019). "Apolipoprotein E (ApoE) deficiency has long been implicated in cardiovascular disease in humans." (PMID 30305304, 2018). "ApoE deficiency has been reported to cause significant lipid disorders and cardiovascular disease." (PMID 26252223, 2015). "Again there is the consideration that this lower ApoE population frequency may associate with a lower baseline frequency and risk of cardiovascular disease early mortality." (PMID 25773008, 2015). "Recent studies on the association between APOE polymorphism and risk of cardiovascular disease had reached similar conclusions, and more evidence could be found in studies on APOE polymorphism and lipid levels." (PMID 26380972, 2015). "Apolipoprotein E (APOE) gene polymorphism can affect APOE gene transcription, serum lipid levels and repair of tissue damage, which could place individuals at serious risk of cardiovascular disease or certain infectious diseases." (PMID 25574218, 2015). "This is a limitation since the presence of the APOE-4 allele carrier is also a risk factor for cardiovascular diseases and may be associated with variations in brain structure and functioning, even in non-elderly adults." (PMID 25520654, 2014). "Epidemiological studies analysed ApoE polymorphism impact on cardiovascular disease." (PMID 25413697, 2014). "In the patients the high-fat meals were associated with blunted decrease in the augmentation index as well as an elevation of chylomicron remnants (high apoB-48 and low apoE), which may contribute to a higher risk of cardiovascular disease." (PMID 24959195, 2014). "APOE gene polymorphisms seem to have some impact among patients with cardiovascular disease." (PMID 24456740, 2014). "LPL, apoE, and PPARα are known as important components of lipid metabolism with roles in the homeostasis of different lipoprotein fractions and their transport, and the polymorphisms of these genes have been associated with cardiovascular diseases." (PMID 25242866, 2014). "However, the three common isoforms of APOE have major effects on lipoprotein fractions and subsequent risk of cardiovascular disease as well as drug prescribing." (PMID 21215387, 2011). "However, given the strong associations with lipid profiles in these children, APOE genotype should be considered important in the context of the origins of cardiovascular disease." (PMID 21215387, 2011).